RTL1 (retrotransposon Gag like 1)
Diseases named in the same sentence as RTL1 in open-access papers (continued):
Sharing a sentence is not in itself a finding about the gene and the disease.
osteosarcoma (1 paper, 2016). A usually aggressive malignant bone-forming mesenchymal neoplasm, predominantly affecting adolescents and young adults. "We found that Dio3 and Rtl1, the paternally expressed genes, were dramatically decreased in the DMR hypomethylated samples but had no significant change in the hypermethylated samples, again consistent with the human osteosarcoma samples." (PMID 26802029, 2016). "It has previously been reported that MEG3 is a tumor suppressor gene, but RTL1 and DIO3 remain candidate genes of interest and have not been well studied in osteosarcoma." (PMID 26802029, 2016).
serous ovarian cancer (1 paper, 2018). "miR-433 is embedded antisense within RTL1 (retrotransposon Gag like 1) and is associated with poor progression-free survival in high-grade serous ovarian cancer patients." (PMID 30114287, 2018).
Spastic paraplegia (1 paper, 2020). Complete loss of the ability to move the lower limbs accompanied by spasticity of the lower limbs. "In this family, which presented with ID, spastic paraplegia and visual impairments, two genetic variations within two different genes (NSL1 and RTL1) were identified." (PMID 31969655, 2020).
squamous cell carcinoma (1 paper, 2017). A carcinoma arising from squamous epithelial cells. "Recently, it has been reported that the expression level of RTL1 was significantly increased in the squamous cell carcinoma of head and neck, but the function of RTL1 was not described." (PMID 29285312, 2017).
Wilms tumor (1 paper, 2024). An embryonal neoplasm characterized by the presence of epithelial, mesenchymal, and blastema components. "Lastly, we identified RTL1 as a candidate marker for tumors with unfavorable prognosis due to loss of imprinting of the maternal allele, similar to earlier reports on loss of imprinting of the IGF2 gene in Wilms’ tumors." (PMID 39635126, 2024).
cancer (8 papers, 2012 to 2024). A tumor composed of atypical neoplastic, often pleomorphic cells that invade other tissues. "Interestingly, RTL1 has recently been reported to be associated with the development of several cancers." (PMID 29285312, 2017). "The model signature genes RSPH9, RPS6KL1, RXFP1, and RTL1 have been revealed to be involved in cancer activity." (PMID 31886214, 2019). "Further research is required to uncover the cancer-modulatory effects of RTL1 in vivo." (PMID 38707901, 2024). "Both PEG10 and RTL1 are considered to act as a driving factor in certain types of cancer." (PMID 37842090, 2023). "Furthermore, ectopic overexpression of Rtl1 in mouse livers induced HCC, validating Rtl1 as a novel cancer driver." (PMID 26481584, 2015). "MiR-127 gene is located in the imprinted region Dlk1/Gtl2 and transcribed in an antisense orientation to a retrotransposon-like gene (Rtl1), and the expression of miR-127 has been shown to undergo DNA methylation regulation in mouse embryos and human cancer cells." (PMID 22720056, 2012). "Understanding these mechanisms should provide a basis for discovering new molecular targets for effective cancer immunotherapy, and PEG10 and RTL1 are examples of how this might work." (PMID 37842090, 2023).
tumor (8 papers, 2013 to 2024). "We have validated Rtl1 as a driver of HCC by demonstrating that its overexpression in mouse liver causes tumor formation." (PMID 23593033, 2013). "RTL1 is the key member of the Dlk1-Dio3 imprinted region, and the loss of imprinting in this region and network disorder of imprint regulation are closely related to tumour formation." (PMID 29285312, 2017). "The results showed that RTL1 overexpression increased the tumour size and weight, whereas knockdown of RTL1 had the opposite effects." (PMID 29285312, 2017). "Overexpression of Rtl1 in the livers of adult mice using a hydrodynamic gene delivery technique resulted in highly penetrant (86%) tumor formation." (PMID 23593033, 2013). "In vivo RTL1 overexpression in the liver contributed to tumor growth." (PMID 29435111, 2018). "Furthermore, in an immunohistochemistry assay, we observed that the expression levels of RTL1, c-MYC, CYCLIN D1 and β-CATENIN in tumour tissues were increased after overexpression of RTL1 and decreased with RTL1 knockdown, in agreement with previous findings in A375 cells." (PMID 29285312, 2017).
infection (2 papers, 2015 to 2023). The state of being infected such as from the introduction of a foreign agent such as serum, vaccine, antigenic substance or organism. "Infection with the Tobacco rattle virus (TRV), which also encodes a VSR limiting PTGS amplification, induces RTL1 as well to reduce siRNA accumulation and promote infection." (PMID 36696453, 2023). "Similarly, Tobacco rattle virus (TRV), which also encodes a weak VSR, induces RTL1 to reduce siRNA accumulation and promote infection." (PMID 36696453, 2023). "Because a fraction of the seeds harvested on TYMV-infected Arabidopsis plants transmit the virus and develop symptoms similar to those observed after mechanical infection, we investigated whether the rtl1 mutation could affect the frequency of TYMV transmission through seeds." (PMID 36696453, 2023). "RTL1 is induced upon infection with a range of viruses, but the VSRs encoded by these viruses inhibit RTL1 activity, suggesting that RTL1 acts in plant antiviral defense while viruses have evolved counterdefenses that inhibit both RTL1 and RNA silencing defenses." (PMID 26696443, 2015). "Given that TYMV successfully infect Arabidopsis, we asked if TYMV could take advantage of the endogenous RNASE-THREE-LIKE1 (RTL1) to achieve its infection." (PMID 36696453, 2023). "Together, these results indicate that RTL1 favors TYMV infection not only when expressed artificially at high level using a p35S:RTL1 transgene but also when expressed at physiological level during infection of WT plants." (PMID 36696453, 2023). "In fact, RTL1 appears to help TYMV to achieve a successful infection." (PMID 26696443, 2015). "Therefore, we attempted to address the biological role of RTL1 in plant–virus interactions by comparing the responses of Col and 35S:RTL1-Flag#2 plants after infection with the four representative viruses used in our previous experiments." (PMID 26696443, 2015). "Indeed, 35S:RTL1 plants exhibit hypersusceptibility to infection by TYMV." (PMID 26696443, 2015). "TCV- and TVCV-inoculated 35S:RTL1-Flag plants developed severe symptoms similar to TCV- and TVCV-inoculated Col, and all these plants eventually died from the infection." (PMID 26696443, 2015). "Indeed, whereas TYMV-inoculated Col only showed mild symptoms and were able to bolt, flower and set seeds, TYMV-inoculated 35S:RTL1-Flag resembled TCV- and TVCV- inoculated Col, which are unable to bolt and which eventually die from the infection." (PMID 26696443, 2015). "However, our results suggest that viruses also inhibit RTL1 activity, suggesting that inhibition of both RTL1 and PTGS is necessary to successfully establish infection." (PMID 26696443, 2015). "We indeed observed that RTL1, but not RTL2 or RTL3, is induced in leaves in response to infection by viruses from four different families, consistent with a possible role of RTL1 in plant–virus interactions." (PMID 26696443, 2015).
adenocarcinoma (1 paper, 2019). A common cancer characterized by the presence of malignant glandular cells. "The expression levels of RRAGB, RSPH9, RPS6KL1, RXFP1, and RTL1 mRNA were significantly lower and the RRM2 mRNA level was significantly higher in the high-risk group than those in the low-risk group in NSCLC adenocarcinoma of GSE11969." (PMID 31886214, 2019). "This signature and the genes RRAGB, RSPH9, RPS6KL1, RXFP1, RRM2, and RTL1 included in this model are independent biomarkers for prediction of overall survival of NSCLC adenocarcinoma." (PMID 31886214, 2019). "Our six-gene prognostic signature for NSCLC adenocarcinoma include RRAGB, RSPH9, RPS6KL1, RXFP1, RRM2, and RTL1 genes which are not contained in the previous gene signatures." (PMID 31886214, 2019).
RTL1 also shares sentences with these, for which no sentence is quoted: cutaneous melanoma (2 papers); memory impairment (2); neurodevelopmental disorder (2); thyroid cancer (2); autism spectrum disorder (1); autoimmune disease (1); basal cell carcinoma (1); bladder tumor (1); cognitive disorder (1); cutaneous squamous cell carcinoma (1); depression (1); encephalomyelitis (1); liver disease (1); migraine disorder (1); neuralgia (1); nevus (1); peripheral neuropathy (1); respiratory failure (1).